MACROD1 (mono-ADP ribosylhydrolase 1)
Description:
Removes ADP-ribose from aspartate and glutamate residues in proteins bearing a single ADP-ribose moiety. Inactive towards proteins bearing poly-ADP-ribose. Deacetylates O-acetyl-ADP ribose, a signaling molecule generated by the deacetylation of acetylated lysine residues in histones and other proteins. Plays a role in estrogen signaling. Binds to androgen receptor (AR) and amplifies the transactivation function of AR in response to androgen. May play an important role in carcinogenesis and/or progression of hormone-dependent cancers by feed-forward mechanism that activates ESR1 transactivation. Could be an ESR1 coactivator, providing a positive feedback regulatory loop for ESR1 signal transduction. Could be involved in invasive growth by down-regulating CDH1 in endometrial cancer cells. Enhances ESR1-mediated transcription activity.
Synonyms: LRP16
Tractability: Small molecule: a structure with a bound ligand is known. PROTAC: UniProt records ubiquitination sites on it; ubiquitination databases record sites on it; its protein half-life has been measured; a small molecule that binds it is known.
Target class: Enzyme; Hydrolase
Gene: Protein-coding gene on chromosome 11 (63,998,553 to 64,166,482, reverse strand). Ensembl gene ENSG00000133315.
Subcellular location: Nucleus
Subcellular location (Human Protein Atlas): Nucleoplasm
Gene Ontology:
Molecular function: ADP-ribosylglutamate hydrolase activity; deacetylase activity; hydrolase activity, acting on glycosyl bonds; protein binding; O-acetyl-ADP-ribose deacetylase activity
Biological process: DNA damage response; peptidyl-glutamate ADP-deribosylation; protein de-ADP-ribosylation; purine nucleoside metabolic process
Cellular component: mitochondrion; nucleoplasm; nucleus
Genetic constraint (gnomAD): Loss-of-function variants: 31 observed, 31.54 expected, observed/expected ratio (o/e) 0.98, 90% interval 0.74 to 1.33. The synonymous counts are far from expectation, so gnomAD's model fits this gene poorly and the ratio says little. Missense variants: 473 observed, 373.2 expected, observed/expected ratio (o/e) 1.27, 90% interval 1.17 to 1.37. Synonymous variants: 252 observed, 157.3 expected, observed/expected ratio (o/e) 1.6, 90% interval 1.45 to 1.78.
Homologues: Orthologues: chimpanzee MACROD1 (99% identical), macaque MACROD1 (97% identical), mouse Macrod1 (86% identical), guinea pig MACROD1 (85% identical), rat Macrod1 (84% identical), dog MACROD1 (84% identical), pig MACROD1 (78% identical), tropical clawed frog macrod1 (52% identical), zebrafish macrod1 (41% identical). Paralogues in human: MACROD2 (39% identical), GDAP2 (23% identical).
Diseases named in the same sentence as MACROD1 in open-access papers:
MACROD1 is named in the same sentence as 25 diseases in open-access papers, as found by Europe PMC text mining. Sharing a sentence is not in itself a finding about the gene and the disease. The quoted sentences say what the papers report.
breast carcinoma (9 papers, 2009 to 2024). "The data correlate well with the human RNA data, with TARG1 being most ubiquitously expressed, MACROD1 more specifically enriched in a number of cell lines, amongst which the rhabdomyosarcoma cell line RD and also breast cancer line MCF7." (PMID 32427867, 2020). "Whilst there is some evidence that MacroD1 expression regulates cell proliferation in human breast cancer MCF-7 cells, little is known about the physiological role of MacroD1 in humans." (PMID 29410655, 2018).
cervical cancer (2 papers, 2009 to 2021). A primary or metastatic malignant neoplasm involving the cervix. "Then, we performed luciferase-based E2-ESR1 reporter assay using WAPL KD and MACROD1 KD human cervical cancer cells." (PMID 33947962, 2021). "However, there are no reports indicating that MACROD1 is associated with the development of cervical cancer." (PMID 33947962, 2021). "However, there have been no reports of an association between MACROD1 and cervical cancer." (PMID 33947962, 2021).
prostate carcinoma (2 papers, 2011 to 2015). A carcinoma that arises from epithelial cells of the prostate gland. "In analogy to its role in ERα signaling, MACROD1 interacts with and stimulates the transcriptional activity of the androgen receptor (AR) and in AR responsive prostate cancer cells, MACROD1 is needed for cell proliferation stimulated by testosterone." (PMID 26426055, 2015).
psoriasis (2 papers, 2021 to 2024). An autoimmune condition characterized by red, well-delineated plaques with silvery scales that are usually on the extensor surfaces and scalp. "For WHRadjBMI and psoriasis, the most significant shared SNP (rs56348466, pCAPSSOC=2.09×10-8) was near MACROD1 and FLRT1." (PMID 38550599, 2024). "Although no alteration in the expression profile of the gene encoding PARG was found, the transcript levels of the genes encoding several PAR hydrolases, namely MACROD1, MACROD2, and TARG1 were lower in psoriasis lesional skin." (PMID 34748530, 2021).
rhabdomyosarcoma (2 papers, 2020). A rare aggressive malignant mesenchymal neoplasm arising from skeletal muscle. "CRISPR-mediated MACROD1 knockout rhabdomyosarcoma cells and MACROD1 knockout mice appear viable, which makes it unlikely that loss of MACROD1 has a drastic growth inhibitory or developmental effect." (PMID 32151005, 2020).
cervical adenocarcinoma (1 paper, 2021). An adenocarcinoma arising from the cervical epithelium. "Therefore, to investigate the correlation between MACROD1 and WAPL, we examined the effects of WAPL KD on MACROD1 in a human cervical SCC cell line SiHa and a human cervical adenocarcinoma cell line HeLa." (PMID 33947962, 2021).
leukaemia (1 paper, 2020). "For MACROD1, a RUNX-MACROD1 fusion was identified in leukaemia and, for MACROD2, a PDGFRA-MACROD2 fusion in a pleomorphic sarcoma." (PMID 32151005, 2020).
neuroblastoma (1 paper, 2020). Neuroblastoma (NB) is the most common solid, extracranial childhood tumor. "MACROD1 is most prevalent in mitochondria of skeletal muscle, MACROD2 localises to nucleo- and cytoplasm and is found so far only in neuroblastoma cells, whereas the more ubiquitously expressed TARG1 is present in nucleoplasm, nucleolus and stress granules." (PMID 32427867, 2020).
osteosarcoma (1 paper, 2018). A usually aggressive malignant bone-forming mesenchymal neoplasm, predominantly affecting adolescents and young adults. "MacroD1 was highly overexpressed in the RD cell line, relative to osteosarcoma (U2OS) cells where only low MacroD1 protein expression was detected." (PMID 29410655, 2018).
sarcoidosis (1 paper, 2025). Sarcoidosis is a multisystemic disorder of unknown cause characterized by the formation of immune granulomas in involved organs. "Finally, at least 8 additional genes have been implicated in immune regulatory response, whereas no clear evidence linking ACOXL, MAT1A, or MACROD1 to sarcoidosis or immune (dys)regulation was found from the available literature." (PMID 41466414, 2025). "Finally, no clear evidence linking ACOXL, MAT1A, or MACROD1 to sarcoidosis or immune (dys)regulation was found from the available literature." (PMID 41466414, 2025).
tendinopathy (1 paper, 2021). "We identified the potential of tendon disease early diagnosis way and immune gene regulation MACROD1 key infiltration characteristics based on comprehensive bioinformatics analysis." (PMID 34714891, 2021). "It is necessary for us to study clearly the function of MACROD1 gene in mitochondria and the possible specific molecular mechanism of the early occurrence of tendinopathy." (PMID 34714891, 2021). "In short, we speculate that the MACROD1 gene may be a potential hub gene for early tendinopathy." (PMID 34714891, 2021). "Therefore, it can be considered that the MACROD1 gene may promote the misdifferentiation of tendon cells by mediating the hypoxic microenvironment of the cells and ultimately lead to tendinopathy." (PMID 34714891, 2021). "By exploring the mechanism of MACROD1 gene in mitochondria and the characteristics of immune cell infiltration, we can find new therapeutic targets in molecular pathways, which may be a promising treatment method for tendinopathy." (PMID 34714891, 2021).
cancer (9 papers, 2011 to 2025). A tumor composed of atypical neoplastic, often pleomorphic cells that invade other tissues. "In carcinomas, the genes related to cell adhesion molecules are MACROD1, CELSR1, and PKP4, with a high-impact mutation detected in PKP4." (PMID 40446009, 2025). "Dysregulation of MacroD1 expression has been shown to be associated with the pathogenesis of several forms of cancer." (PMID 29410655, 2018). "Previous studies have focused on illuminating the association between MacroD1 dysregulation and cancer development." (PMID 29410655, 2018). "Earlier studies have implicated MacroD1 expression (previously known as LRP16 – leukemia related protein 16) in the pathophysiology of several human cancers." (PMID 29410655, 2018). "Future work will have to dissect in which context loss or gain of MACROD1 may be driving aspects of cancer growth." (PMID 32151005, 2020). "Several studies point to an association of MACROD1 (LRP16) with cancer." (PMID 26426055, 2015). "In this review, we critically assess the available literature on a role for the hydrolases in cancer and find that, currently, there is limited evidence for a role for MACROD1, MACROD2, or TARG1 in tumorigenesis." (PMID 32151005, 2020). "MACROD1, MACROD2, and OARD1 (TARG1) exhibit mutations only in 0.9%, 2.6%, and 1% of cancer patient samples, respectively, from over 1000 samples in the cBioPortal curated dataset." (PMID 32151005, 2020). "Based on our findings and the positive correlation between MacroD1 and cancer invasiveness, MacroD1 might be an attractive new target for cancer therapy." (PMID 40817374, 2025). "Expressed in many tissues, MACROD1 abundance is elevated in several types of cancers." (PMID 36173347, 2022). "Also, several genes of cancer suppressors were activated after mitochondrial administration, including Csad, Ccdc30, Macrod1, Pcdh1, Tprkb, and Hdac11." (PMID 34131403, 2021). "Furthermore, we show that MacroD1 is differentially expressed in a tissue-specific manner in human and mouse tissues and human cancer cell lines." (PMID 29410655, 2018). "Despite the presence of several publications reporting a correlation between MACROD1 or MACROD2 levels and cancer development or progression, it is not clear at the moment that they have a causative role." (PMID 32151005, 2020).
tumor (7 papers, 2009 to 2025). "Several follow-up studies linked the effect that MacroD1 had on tumor growth and progression with estrogen- and androgen-receptor signaling." (PMID 40817374, 2025). "Despite the low number of identified mutations in patient tumour samples, several reports have correlated MACROD1 or MACROD2 expression levels with the clinical outcome, as described in the next paragraphs." (PMID 32151005, 2020). "Generally, MacroD1 expression levels positively correlate with proliferation rates and tumor invasiveness." (PMID 40817374, 2025). "MACROD1 expression was shown to be upregulated by oestrogen, which leads to several studies of the role of MACROD1 in tumours with a differential oestrogen status." (PMID 32151005, 2020). "Despite these technical challenges, multiple studies have correlated tumour growth with MACROD1 expression in either xenograft models or in patient cohorts." (PMID 32151005, 2020). "Cells overexpressing MACROD1 had a higher tumour volume and a lower survival rate." (PMID 32151005, 2020). "Cells lacking MACROD1 had a lower tumour-forming potential and higher survival rate." (PMID 32151005, 2020). "Furthermore, when delivered into nude mice, cells overexpressing MACROD1 lead to a decreased tumour volume and have a lower metastatic potential compared to cells without overexpressed MACROD1." (PMID 32151005, 2020).
MACROD1 also shares sentences with these, for which no sentence is quoted: breast tumor (2 papers); colorectal carcinoma (2); Anxiety (1); attention deficit-hyperactivity disorder (1); autism (1); endometrial cancer (1); gastric cancer (1); lung carcinoma (1); monocytic leukemia (1); Obesity (1); ovary cancer (1); schizophrenia (1).